ALB (albumin)
Diseases named in the same sentence as ALB in open-access papers (continued):
Sharing a sentence is not in itself a finding about the gene and the disease.
cancer (continued). "The development of albumin drug carriers is gaining increasing importance in the targeted delivery of cancer therapy, particularly as a result of the market approval of the paclitaxel-loaded albumin nanoparticle, Abraxane®." (PMID 25161624, 2014). "In multivariate analyses, cancer and serum albumin were positively correlated, and IDWL and hemoglobin were negatively correlated with sNa." (PMID 24354674, 2013). "Same group in a recent study assessing the outcome of the modified GPS in a lager cohort (n = 8759) reported that 90% of cancer patients with a low albumin level had an elevated CRP." (PMID 23590192, 2013). "The topic of the current review is the nanoparticle albumin bound paclitaxel (nab-paclitaxel) development, which has opened a novel scenario in cancer treatment by the enhancement of paclitaxel delivery by the use of nanotechnology." (PMID 23738077, 2013). "In conclusion, this study revealed an association of RDW values with PS, albumin levels, WBC counts, platelet counts, the presence of comorbid disease and clinical cancer stage." (PMID 24244659, 2013). "Loading of cancer drugs into albumin-based nanoparticles was achieved by coacervation of disulfide bond reduced BSA and thiolated alginate (alginate-cysteine conjugate)." (PMID 23344060, 2013). "Nanoparticle albumin bound paclitaxel (nab-paclitaxel) represents the first nanotechnology-based drug in cancer treatment." (PMID 23738077, 2013). "The same results were also reported in the Glasgow Prognostic Score (GPS) system, a prognosis model based on CRP and albumin, which can effectively predict the treatment outcome of various cancers." (PMID 24130817, 2013). "Soluble albumin and albumin nanoparticles are currently used as a delivery vehicle in chemotherapy as they are known to accumulate and to be catabolized by cancerous tumors." (PMID 22891637, 2012). "Median CRP and albumin measured in the normal and abnormal groups were both within normal ranges and the distribution of cancer types was broadly similar." (PMID 22588559, 2012). "A score based on serum concentrations of C-reactive protein (CRP), albumin, gamma-glutamyl transferase (GGT), and HDL cholesterol was positively associated with death from cancer, circulatory disease, and all-cause mortality." (PMID 23092358, 2012). "Cancer death was positively associated with age, male sex, systolic blood pressure, HbA1c, BUN, creatinine, and smoking and inversely associated with albumin and total cholesterol." (PMID 22672958, 2012). "The scope of this short review is to summarise the knowledge gleaned from the fate of drugs transported by albumin upon contact with the target cancer cell or cells in inflamed tissues." (PMID 21676260, 2011). "Patients (n=21 669) who had an incidental blood sample taken between 2000 and 2006 for C-reactive protein, albumin and calcium (and liver function tests where available) and a diagnosis of cancer were identified." (PMID 21266974, 2011). "A low albumin, an elevated mGPS, C-reactive protein, adjusted calcium, bilirubin, Alk phos, AST, ALT and GGT were associated with a reduced 5-year overall and cancer-specific survival (all P<0.001)." (PMID 21266974, 2011). "The potential advantage of serum albumin level as a pretreatment prognostic factor in cancer patients is that it is inexpensive, reproducible and powerful." (PMID 21176210, 2010). "There are several methods of assessing nutritional status in cancer of which serum albumin is one of the most commonly used." (PMID 21176210, 2010). "Patients with cancer had higher C-reactive protein and lower albumin levels (and thus a higher mGPS), higher adjusted calcium, Alk phos and GGT levels, but lower aspartate transaminase (AST) and alanine transaminase (ALT) levels (all P<0.001)." (PMID 20717110, 2010).
cancer (continued). "The inverse correlation between body weight index and albumin synthesis in cancer patients supports the possibility of a compensatory enhanced albumin synthesis in these metabolically affected patients." (PMID 21176210, 2010). "In this paper, we systematically review all available epidemiologic literature on the relationship between pretreatment serum albumin and cancer mortality." (PMID 21176210, 2010). "We therefore reviewed all available epidemiological literature (published within the last 15 years) to summarize the role of pretreatment serum albumin as an independent predictor of survival in cancer." (PMID 21176210, 2010). "There were higher circulating concentrations of C-reactive protein and lower albumin levels (and thus a higher proportion of mGPS 1 or 2), in those patients with cancer (all P<0.001)." (PMID 20717110, 2010). "Despite these limitations, we believe that the extensive available literature reviewed here demonstrates a strong prognostic role of serum albumin in predicting cancer survival." (PMID 21176210, 2010). "When these biochemical parameters, together with bilirubin and ALT, were regressed against the presence of cancer, C-reactive protein, albumin, adjusted calcium, Alk phos and GGT were all shown to be independently associated with the presence of cancer." (PMID 20717110, 2010). "Patients with an elevated C-reactive protein, adjusted calcium, Alk phos and GGT levels or low albumin levels were more likely to have cancer (all P<0.001)." (PMID 20717110, 2010). "Research conducted over the last decade or so has demonstrated that serum albumin levels (either considered alone or in combination with other parameters) can provide useful prognostic information in a variety of cancers." (PMID 21176210, 2010). "Patients following a diagnosis of cancer had lower albumin levels and thus higher mGPS (all P<0.001)." (PMID 20717110, 2010). "Serum albumin has also been described as an independent prognosticator of survival in various cancers like lung, pancreatic, gastric, colorectal and breast." (PMID 21176210, 2010). "A systematic search of the literature using the MEDLINE database (January 1995 through June 2010) to identify epidemiologic studies on the relationship between serum albumin and cancer survival." (PMID 21176210, 2010). "Albumin, protein and haemoglobin are serum markers which show the nutritional status in patients with cancer." (PMID 19635171, 2009). "CRC patients with serum CEA level < 5 ng/ml (P < 0.001) or albumin level ≥ 3.5 gm/dl (P < 0.001) had significantly greater cancer-specific survival rates than those with serum CEA levels ≥ 5 ng/ml or albumin level <3.5 gm/dl respectively." (PMID 19691850, 2009). "Only pre-operative albumin concentration, locoregional and systemic treatments were independent predictors of cancer-specific survival." (PMID 18797461, 2008). "BMI and albumin were lower (P<0.05) and white cell count (P<0.001) and C-reactive protein (P<0.001) were higher in cancer patients compared with controls." (PMID 15570310, 2004). "Of the other parameters measured, only plasma albumin level was found to vary significantly amongst the 3 categories, the mean level being the lowest in cachectic cancer patients." (PMID 698044, 1978). "Nima Beheshtizadeh and research collaborators comprehensively analyzed the transformative potential of docetaxel-loaded nanoplatforms in oncology, establishing that albumin-based delivery systems represent a paradigm shift in chemotherapeutic efficacy for cancer treatment." (PMID 41489768, 2026). "Thus, oncogenic Ras signaling promotes the nutritional utilization of albumin by suppressing FcRn, thereby supporting cancer cell adaptation to nutrient-poor environments." (PMID 42056637, 2026). "A recent study investigating appetite in late-stage cancer patients indicated that albumin levels were associated with loss of appetite in men but not in women." (PMID 41504962, 2026).
cancer (continued). "Using NHANES 2007-2012 data (15,854 participants, 1472 with cancer), we examined whether the lactate-dehydrogenase-to-albumin ratio (LAR) predicts respiratory mortality." (PMID 41650042, 2026). "Finally, it outlines the latest approaches in multimodal theranostic platforms, highlighting albumin's potential to improve cancer therapy." (PMID 41599237, 2026). "Various inflammatory mediators such as tumor necrosis factor (TNF), which augments microvascular leakiness, along with interleukin-1 (IL-1) and interleukin-6 (IL-6), known to suppress albumin production, contribute to the observed decrease in serum albumin among cancer-afflicted individuals." (PMID 40034601, 2025). "Very few studies were found examining either calcium or albumin, cancer incidence, and ethnicity." (PMID 40941010, 2025). "The albumin‐curcumin system showed enhanced cytotoxicity due to the improved intracellular accumulation of curcumin as a result of the active targeting of albumin to cancer cells via gp‐60‐overexpressing cancer cells." (PMID 40190185, 2025). "ALB plays a critical role in patient nutrition, cancer progression, and immunity." (PMID 40013138, 2025). "Moreover, albumin interacts with gp60 receptors, which are overexpressed in tumors; therefore, it is used as a targeted drug delivery system for cancers." (PMID 40190185, 2025). "However, other predictors with an increased incidence of unplanned visits included female patients, patients with chronic kidney disease stage 3 to 5, cancer and serum albumin levels below 4 g/dL." (PMID 41331911, 2025). "The HALP score is considered as a potential predictor of cancer prognosis because it combines four indicators, namely haemoglobin, albumin, lymphocytes and platelets, which can comprehensively reflect the systemic inflammatory response and nutritional status of cancer patients." (PMID 40642085, 2025). "Notably, serum albumin levels have been identified as an independent prognostic factor for survival across multiple cancer types." (PMID 40869526, 2025). "Interestingly, reports support that albumin accumulates at cancer sites with vascular leakiness where it is metabolized as an energy source." (PMID 40041621, 2025). "High catabolism in patients with cancer leads to increased ALB consumption, and with the progression of the disease, increased capillary permeability leads to the infiltration of ALB into the interstitial space, resulting in the formation of exudates in the serosal cavities." (PMID 39886546, 2025). "Moreover, Hallmark gene set for cancer‐related pathways (e.g., EMT, IL6 and TNFα signals) were exclusively enriched in ALB+KRT7+ EPCs from AC samples." (PMID 39834100, 2025). "Across all sites, the OR of cancer diagnosis within a year of the test for patients with low albumin compared to normal albumin was 3.2 for White patients (95% CI 3.1, 3.3), 3.8 for Asian patients (95% CI 3.3, 4.4), and 3.3 for Black patients (95% CI 2.8, 4.0)." (PMID 40941010, 2025). "Low levels of albumin are frequently observed in cancer patients, which may indicate a lower nutritional condition and may disrupt immunological processes like phagocytosis and humoral and cellular immunity." (PMID 41142623, 2025). "As a modular approach, hitchhiking STING agonists on serum albumin may serve as a broadly applicable strategy for augmenting the potency of systemically administered cancer immunotherapies." (PMID 40500332, 2025). "Similarly, nutritional status is also a key factor in cancer treatment outcomes, and serum albumin is a marker of nutritional state and overall health." (PMID 40217668, 2025). "Low levels of albumin are frequently observed in cancer patients, which may indicate a lower nutritional condition and could affect immunological processes like phagocytosis and humoral and cellular immunity." (PMID 41142623, 2025).
cancer (continued). "Furthermore, anti-tumor assessment using Ehrlich tumor and histopathological study confirmed the augmented anti-cancer effect of ALB when incorporated in SA-EC-ALB." (PMID 40978467, 2025). "Additionally, data from the American Cancer Society revealed that, in 2020, there were 1,806,590 new cancer cases in the United States, further underscoring the importance of albumin." (PMID 40699702, 2025). "Angiogenesis by malignant tumors may contribute to a higher signal too as the blood contains high concentrations of hemoglobin and albumin." (PMID 39891260, 2025). "Serum albumin, although affected by factors beyond nutrition, remains a widely used marker associated with prognosis and perioperative risk, while C-reactive protein (CRP) and composite indices incorporating CRP and albumin are used to evaluate the inflammatory component of cancer cachexia." (PMID 41463399, 2025). "It should be highlighted that gp60 allows albumin to participate in the specific targeting of cancerous cells because it mediates the transportation of medicines in albumin-based drug delivery systems via biological, epithelial, and endothelial barriers, undergoing overexpression in cancer cells." (PMID 40006569, 2025). "According to some authors, elevated ALB values are associated with lower ALP levels in cancer patients, but this observation was not confirmed in the present study." (PMID 40725214, 2025). "The concept of a composite inflammatory-nutritional index is not entirely novel; the prognostic nutritional index and the CRP/albumin ratio have both been linked to cancer outcomes in cardiac and non-cardiac settings." (PMID 41473193, 2025). "Furthermore, they have low haemolytic potential, effectively inhibit heat‐induced albumin denaturation to reduce inflammation, selectively target cancer cells, and possess broad‐spectrum antimicrobial properties." (PMID 39417784, 2025). "Similarly, GNRI incorporates serum albumin and body weight and has been widely used as a prognostic marker in elderly or cancer patients." (PMID 41334338, 2025). "The 2S albumin from pumpkin seeds has been proven to possess strong anticancer activity, exerting significant cytotoxic effects on various cancer cell lines such as breast cancer (MCF-7), ovarian teratocarcinoma (PA-1), prostate cancer (PC-3 and DU-145), and hepatocellular carcinoma (HepG2)." (PMID 41300124, 2025). "Beyond albumin, cancer cells utilize AAs derived from the breakdown of host tissues, notably skeletal muscle and skin, leading to sarcopenia, cachexia, and hypoalbuminemia, clinical indicators of disrupted systemic protein homeostasis and poor patient outcomes." (PMID 40944200, 2025). "In cancer-associated inflammatory states, inflammatory cytokines such as IL-6 and TNF-α not only stimulate the synthesis of CRP but also inhibit the synthesis of albumin, accelerate its degradation, and promote vascular extravasation." (PMID 41415846, 2025). "In parallel, serum proteins such as albumin, α1-globulin, and α2-globulin—measured through serum protein electrophoresis (SPE)—are well-established markers of systemic inflammation, and alterations in their levels have been associated with malignancy." (PMID 40362613, 2025). "Subsequent research indicates that the anticancer mechanism of pumpkin 2S albumin was mediated by the induction of apoptosis in cancer cells, as evidenced by acridine orange–ethidium bromide staining and DNA fragmentation analysis, with its apoptotic effect being dose-dependent." (PMID 41300124, 2025). "Similarly, another study developed human serum albumin-indocyanine green NPs (HSA-ICG NPs) through disulfide conjugations to enhance phototherapy for cancer treatment." (PMID 41048541, 2025). "Albumin is considered a separate prognostic factor for various cancer types." (PMID 40786260, 2025). "Interestingly, low albumin and creatinine kinase level were correlated with a higher rate of cancer." (PMID 39829143, 2025).
cancer (continued). "Thus, on the other hand, the decision to include albumin as an important serum marker for nutritional status in cancer patients cannot be an accurate one." (PMID 40806017, 2025). "Albumin has also been recognized as a valuable prognostic biomarker in various cancers." (PMID 40283046, 2025). "Albumin is a plasmatic protein with low levels in inflammatory states and cancers." (PMID 40149324, 2025). "Previous studies have shown that low serum albumin levels correlate with poor cancer prognosis." (PMID 40134599, 2025). "For instance, a randomized controlled trial (RCT) conducted in septic cancer patients admitted to the ICU evaluated the effects of administering a bolus of albumin in lactated Ringer’s solution versus lactated Ringer’s solution alone during the initial six hours of fluid resuscitation." (PMID 40699702, 2025). "The albumin and A/G ratio may reflect the nutritional status and severity of disease in cancer patients." (PMID 39862296, 2025). "Notably, in the non‐cancer group, albumin levels were higher, and neutrophil proportion, as well as NPAR were lower." (PMID 39831739, 2025). "Another study reported that serum albumin, uric acid, and neutrophil count significantly mediate the association between the OBS and CRC, suggesting that dietary factors may influence cancer risk through their impact on these biomarkers." (PMID 40005007, 2025). "The PNI, derived from serum albumin levels and total lymphocyte count, serves as an innovative systemic inflammatory marker, providing insight into the nutritional and immunological status of cancer patients." (PMID 40538399, 2025). "In univariate analyses, sex (p = 0.016), cancer treatment type (p = 0.010), albumin level (p < 0.001), disease stage (p < 0.001), unplanned hospital readmission (p < 0.001), ECOG performance status (p < 0.001), and hemoglobin (p = 0.008) were statistically related to overall survival." (PMID 40283507, 2025). "This suggests that both covalent and non-covalent complexes formed with albumin are associated with cellular import, and both forms persist within cancer cells." (PMID 39904854, 2025). "While loss of FcRn expression has been speculated to result in albumin accumulation, associated with poor prognosis, another study reports that FcRn is up-regulated in cancer tissues and suggests that it drives albumin uptake and cancer growth." (PMID 40041621, 2025). "The HALP score, a composite index based on the hemoglobin, albumin, lymphocytes, and platelets, may reflect both nutritional reserves and systemic inflammatory burden, which are known to influence cancer outcomes." (PMID 40528068, 2025). "Declining ALB levels are an independent prognostic factor in cancer." (PMID 40924724, 2025). "Importantly, despite access to a wide range of lipid classes, albumin-bound lipids are the primary species consumed during cancer cell proliferation." (PMID 40027810, 2025). "This may serve as a more reliable prognostic indicator in cancer patients compared to LDH or ALB alone." (PMID 40013138, 2025). "Moreover, internalized albumin-bound paclitaxel exhibits significant immunostimulatory activity, promoting the cancer immunity cycle." (PMID 41550955, 2025). "Serum albumin levels are known to decrease in patients with cancer cachexia." (PMID 40469669, 2025). "Recent evidence suggests that HMCDs bind to serum albumin before cancer cell internalization." (PMID 39904854, 2025). "A number of studies have reported the link between low albumin and generic cancer risk; however, again, no studies were identified reporting the link between low albumin and diagnosis of cancer at an advanced stage." (PMID 40941010, 2025). "Albumin is considered a common marker for assessing nutritional status in cancer patients." (PMID 41568365, 2025).